CDKN2A (cyclin dependent kinase inhibitor 2A)
Diseases named in the same sentence as CDKN2A in open-access papers (continued):
Sharing a sentence is not in itself a finding about the gene and the disease.
lymphoma (90 papers, 2006 to 2025). A malignant (clonal) proliferation of B- lymphocytes or T- lymphocytes which involves the lymph nodes, bone marrow and/or extranodal sites. "A surprising finding from our sequencing of Eμ-Myc lymphomas was the identification of additional putative oncogenic lesions in the context of Cdkn2a loss, namely for lymphomas #4242 (Bcor frameshift deletion), ML353 (KrasQ61H) and #6066 (NrasQ61K)." (PMID 28262675, 2017). "Interestingly, multiple PDCD1-mutant lymphomas carried mutations in another tumor suppressor encoded by CDKN2A." (PMID 37723306, 2023). "Our results indicate that loss of Ptprd in Cdkn2a null mice promotes the development of lymphomas." (PMID 25138050, 2014). "The gene p16 may also potentially be involved in the occurrence of these malignancies since it inhibits the cyclin‐dependent kinase CDK4 (CD4 K and CDKN2A being known melanoma susceptibility genes) and since some mutations of p16 were reported in different types of lymphoma." (PMID 33219744, 2021). "In canine lymphoma cells, inactivation of p16 (CDKN2A) and hyperphosphorylation of its target, pRb, have been reported." (PMID 40872651, 2025). "Somatic microdeletion of 9p21.3 was also reported in a patient with WBS with lymphoma and a homozygous deletion of the INK4a/ARF (or CDKN2A) locus at 9p21.3; however, the relationship between 9p21.3 deletion and lymphoma has not been explained." (PMID 38363891, 2024). "The Eμ-Myc;Cdkn2a−/− cell line, also called MA-LN in this study, is a cell line widely used to establish the lymphoma transplantation model, a type of GDA model." (PMID 37700827, 2023). "Different from Eμ-Myc;Cdkn2a-/- lymphomas, MA lymphomas arising in recipient mice usually colonize in kidney, and at the same time, lymph nodes are often unaffected." (PMID 38077394, 2023). "Eμ-Myc;Cdkn2a-/- cell line is a widely used murine lymphoma cell line to establish the CellDAs model and Eμ-Myc;Cdkn2a-/- lymphomas usually form palpable masses at multiple lymph nodes." (PMID 38077394, 2023). "Currently there is a phase I clinical trial investigating the MAT2A inhibitor AG-270 in advanced solid tumors or lymphomas with homozygous deletions of CDKN2A/B or MTAP (NCT03435250)." (PMID 38017560, 2023). "Because of ease of establishing a syngeneic lymphoma transplantation model, a type of the GEM-derived allograft (GDA) model, the Eμ-Myc;Cdkn2a−/− cell line, which usually gives rise to lymphoma in lymph nodes, is widely used for in vivo efficacy evaluation." (PMID 37700827, 2023). "In indolent lymphoproliferative malignancies, namely CLL and follicular lymphoma, deletions of CDKN2A are rare, and CDKN2A inactivation frequently correlates with the transformation to an aggressive lymphoma with adverse prognosis." (PMID 32751805, 2020). "These analyses indicate that EZH2 (PRC2) can promote growth of lymphoma cells via suppression of cdkn2b and/or cdkn2a." (PMID 32850364, 2020).
lymphoma (continued). "When tumors developed in the offspring, we harvested lymphoma from λ-Myc;CreER;Chek1Flox/D130A;Cdkn2a+/−, λ-Myc;CreER;Chek1Flox/Flox;Cdkn2a+/− or λ-Myc;CreER;Chek1Flox/wt;Cdkn2a+/− mice." (PMID 32571801, 2020). "In some, such as lymphoma, gastric cancer, head and neck squamous cell carcinoma (HNSC), liver and oesophageal cancers, p16INK4A/CDKN2A downregulation is caused by promoter hypermethylation, but it can also be due to histone deacetylase (HDAC) activity." (PMID 28931650, 2017). "CDKN2A loss occurs in >55 % of T-cell lymphomas (T-LSA) and <2 % of other subtypes of canine leukemia and lymphoma." (PMID 27639374, 2016). "The characterization of the CDKN2A status may be important to guide the use of ATRi in lymphoma cells." (PMID 40847617, 2025). "Furthermore, even in wild-type mice, deletion of any one of the tumor suppressor genes Pax5, Sfpi1, Ikzf1, Pten or Cdkn2a has been reported specifically in irradiated animals in copy number analyses of lymphomas, acute myeloid leukemia and thymic lymphoma." (PMID 37117033, 2023). "Furthermore, the MA cell-line transplant model indicates that lymphoma cells themselves are sufficient to lead to lymphoma dissemination behavior, suggesting that the MA cell line can be regarded as a transformed form of Eμ-Myc;Cdkn2a-/- cell line." (PMID 38077394, 2023). "The molecular characteristics of the MCD subtype and the ABC subtype, such as deletion of CDKN2A, BCL2 overexpression, activation of BCR and NF-κB signaling pathways, may be the cause and result of lymphoma losing homing ability." (PMID 38077394, 2023). "Recently, a transcription factor gene, SRY-box transcription factor 4 (SOX4), and the cyclin-dependent kinase inhibitor 2A (CDKN2A), have attracted the attention of researchers as they may play essential roles in lymphoma oncogenesis." (PMID 33923245, 2021). "On the other hand, mice transplanted with lymphoma cells from λ-Myc;CreER;Chek1Flox/D130A;Cdkn2a+/− mice, and to a lesser extent lymphoma cells from λ-Myc;CreER;Chek1Flox/Flox;Cdkn2a+/− mice, exhibited a rapid decrease in white blood cell count upon tamoxifen treatment." (PMID 32571801, 2020). "Notably, Cdkn2a transcript abundance was high in Id2fl/flId3fl/flIL7RCre CD4SP cells but low in lymphoma cells." (PMID 25691468, 2015). "Interestingly, Ptprd−/−Cdkn2a−/− mice developed significantly more lymphomas than Ptprd+/+Cdkn2a−/− mice (p<0.05)." (PMID 25138050, 2014). "In addition, Ptprd+/−Cdkn2a−/− mice showed a trend toward developing more lymphomas than Ptprd+/+Cdkn2a−/− mice." (PMID 25138050, 2014). "The hypermethylation of CDKN2A (p16) promotes uncontrolled fibroblast proliferation and RASSF1A silencing via DNA methylation which prevents apoptosis and plays a important role in cell-cycle arrest and is implicated in the development of a number of different cancers including lymphomas." (PMID 40299416, 2025). "However, our data challenges this hypothesis, at least with regard to the role of Cdkn2a, as more than one putative ‘driver lesion' could be detected in some lymphomas." (PMID 28262675, 2017). "CDKN2A and MTAP genes, which have also been described in lymphomas, specifically in the chemoresistant and ABC type DLBCLs }, were in turn located in the regions of copy number losses at 9p21.3." (PMID 24625556, 2014). "Mice transplanted with λ-Myc;CreER;Chek1Flox/wt;Cdkn2a+/− lymphoma cells did not respond at all to tamoxifen, again demonstrating that one allele of Chek1 is sufficient for lymphoma cells to survive." (PMID 32571801, 2020).
lymphoma (continued). "The pattern of imbalances showing gains in 3q and trisomy 18 as well as homozygous loss in 9p21.3 (encompassing the region of CDKN2A/B) together with the lack of detectable CD10 in the presence of CD20 and BCL2 expression resembles other extra-nodal lymphoma." (PMID 33339535, 2020). "Finally, we discovered that Eμ-Myc lymphomas co-occur with loss of Cdkn2a and either activating mutations in Ras or deleterious mutations in Bcor providing evidence that loss of Cdkn2a alone may not be sufficient to cooperate with overexpressed Myc to drive lymphomagenesis." (PMID 28262675, 2017).
colon carcinoma (88 papers, 2004 to 2026). "The purpose of this study is to apply rs10811661 polymorphism in CDKN2A /B gene as an effective biomarker of colon cancer and early detection of gastric cancer." (PMID 37845622, 2023). "Additionally, it has been reported that CDKN2A is linked to the CpG island methylator phenotype (CIMP) in colon carcinoma, which can promote methylation-mediated gene silencing." (PMID 36160009, 2022). "In addition, there are regional differences in the risk of poor prognosis of colon cancer caused by CDKN2A methylation." (PMID 35311137, 2022). "IHC analysis showed that CDKN2A is primarily expressed in small amounts in the nucleus in normal tissues, while in Colon cancer tissue, its expression is significantly localized to the cytoplasm, with a small amount still present in the nucleus." (PMID 39895793, 2025). "The colon cancer samples were further obtained to verify the correlation between CDKN2A expression and immune cell infiltration by fluorescence staining." (PMID 40560740, 2025). "Fluorescence images of colon cancer from different patients demonstrated a positive correlation between CDKN2A expression and the number of CD45+ immune cells." (PMID 40560740, 2025). "This study contributes to understanding CDKN2A and its relevance in cancer, paving the way for future wet-lab investigations regarding colon cancer." (PMID 38894777, 2024). "We found that shikonin increased the activity of senescence-associated β-galactosidase (SA-β-Gal) in colon cancer cells after downregulation of CXCL8 and CDKN2A through a senescence-associated β-galactosidase (SA-β-Gal) staining experiment." (PMID 39188951, 2024). "The senescence-associated genes CDKN2A and CXCL8 were significantly downregulated in colon cancer cells after shikonin treatment." (PMID 39188951, 2024). "We investigated the correlation between overall survival and CDKN2A expression in colon cancer using a KM plotting mRNA gene chip ID 209644_x_at." (PMID 38894777, 2024). "In sporadic CRC, methylation of CDKN2A was significantly more frequent in colon cancers with a higher tumor grade and lymph node metastasis." (PMID 37845228, 2023). "Another study showed that CDKN2A, as one of the 8 autophagy genes prognostic signature in colon cancer, can be seen as a good biomarker." (PMID 35429970, 2022). "Hypermethylation of the tumor suppressor gene p16INK4a (p16, cyclin-dependent kinase inhibitor 2A) was reversed by quercetin after 120 h of treatment in the human colon cancer cell line RKO." (PMID 36142391, 2022). "We reported previously that MCC and CDKN2A promoter methylation are frequently found in the same colon carcinoma specimens." (PMID 34298744, 2021). "A novel lncRNA, P14AS, transcribed from the antisense strand of the CDKN2A/P14 gene, promotes colon cancer development by cis upregulating the expression of oncogenic ANRIL." (PMID 32106863, 2020). "Such epigenetically silenced genes include CDKN2A (p16), MLH1, APC, and the secreted frizzled related (SFRP) family and are associated with colon cancer." (PMID 28186961, 2017). "Highly connected biomarkers (with degree centrality) were BRAF mutation (0.19) and methylation-related markers including CDKN2A (0.17), IGF2 (0.17), RUNX3 (0.17), CACNA1G (0.15), CRABP1 (0.15), and NEUROG1 (0.15) in the proximal colon cancer network." (PMID 28623901, 2017). "We conclude that expression of CDKN2A is often regulated via methylation, but that this can be best represented by different mRNA probes, for breast and colon cancer." (PMID 26860128, 2016).
colon carcinoma (continued). "In human colon cancer cells, Cdkn2a mRNA expression was induced 24 h after SFN treatment, and immunoblotting corroborated the increased expression of p16 protein." (PMID 26388957, 2015). "Since it has been shown in the human colon cancer cell line HCT116 that downregulation of DNMT1 by siRNA induced a demethylation of the promoter of CDKN2A, we tested in HCT116 the same DNMT1 siRNA that we used in KG1." (PMID 25948775, 2015). "For example, poor prognosis was reported to be associated with low DLC1, low CDKN2A/B and high CDK4 in lung cancer, and low DLC1, low CDKN2B, and high CDK6 in colon cancer." (PMID 25425654, 2014). "Based on these findings, we propose that shikonin may induce senescence in colon cancer cells and inhibit colon cancer progression by downregulating CDKN2A and CXCL8." (PMID 39188951, 2024). "Collectively, these results suggest that shikonin inhibits colon cancer development by downregulating the expression of CDKN2A and CXCL8, which may be involved in cellular senescence." (PMID 39188951, 2024). "In summary, we found that shikonin suppresses colon cancer cell proliferation and migration through cellular experiments and identified eight genes (CCNB3, IL-1α, CXCL8, CDKN2A, MYC, IGFBP3, SQSTM1, and GADD45G) associated with cell senescence through systematic bioinformatics analysis." (PMID 39188951, 2024). "Moreover, in colon cancer cells, the epigenetic silencing of CDKN2A and MLH1 genes was also correlated with enhanced levels of DNMT1 and DNMT3B." (PMID 38504782, 2024). "Based on our observations, we hypothesize that shikonin might play a pivotal role in inducing cellular senescence in colon cancer cells by suppressing the expression of CXCL8 and CDKN2A, ultimately leading to the inhibition of colon cancer development." (PMID 39188951, 2024). "Of these, the frequency of CDKN2A methylation in MSI-L colon tumors is less than that in MSI-H or MSS tumors and might be associated with poor prognoses." (PMID 35962309, 2022). "Nowadays, the CDKN2A gene has been rarely studied in colon cancer." (PMID 35429970, 2022). "Furthermore, the expression levels of DNMT1 and CDKN2A were measured in colon cancer cells following treatment with the DNMT1 inhibitor, 5-azacytidine, and DNMT1 overexpression plasmid." (PMID 33959155, 2021). "Indeed, the up-regulated expression of CDKN2A (p16) in sebaceous carcinoma and colon cancer has been exhibited." (PMID 33896386, 2021). "Meanwhile, knocking down of DNMT1 in colon cancer cells significantly increased the ability of 5-Aza-CdR to increase expression of CDKN2A, indicating that DNMT1 may work additively or synergistically with other members of DNMT in regulating DNA methylation." (PMID 34268315, 2021). "In The Cancer Genome Atlas (TCGA) database, NFE2L2 (Nrf2) levels also varied markedly in normal colon and in colon tumors and were inversely correlated with Cdkn2a/p16, in accordance with data from cell-based, preclinical, and translational studies reported here." (PMID 26388957, 2015). "Interestingly, SFN increased Cdkn2a/p16 mRNA levels in colon tumors of WT mice but had the opposite effect in Nrf2−/+ mice." (PMID 26388957, 2015). "Several studies indicated that cell cycle regulatory gene CDKN2A is hypermethylated in colon cancer cells, and decitabine-induced cell proliferation inhibition may result from the release of methylation silencing of the CDKN2A gene." (PMID 24874286, 2014). "In colon cancer, Kaiso may regulate methylation-dependent inhibition of tumor suppressors such as CDKN2A by binding to its methylated promoter." (PMID 22662240, 2012). "Furthermore, a recent study carried out in colon cancer cell lines suggests that Kaiso is a methylation-dependent "opportunistic" oncogene, which represses the tumor suppressor gene CDKN2A and provides a survival advantage to colon cancer cells." (PMID 19508730, 2009).